PIEZO1 (piezo type mechanosensitive ion channel component 1 (Er blood group))
Diseases named in the same sentence as PIEZO1 in open-access papers (continued):
Sharing a sentence is not in itself a finding about the gene and the disease.
tumor (126 papers, 2012 to 2026). "(2024) used a Piezo1 knockout model to show that its deficiency severely impairs NK cell tumor surveillance, particularly compromising stiffness-dependent cytotoxicity and infiltration into 3D matrices." (PMID 41607548, 2026). "Fourth, PIEZO1 shows positive associations with tumor microenvironment scores (Stromal/Immune/ESTIMATE) and immune checkpoint markers (CD274, CTLA4, LAG3, PDCD1, PDCD1LG2)." (PMID 40977743, 2025). "In our study, Analysis of TCGA data revealed that higher PIEZO1 mRNA expression was associated with reduced overall survival across tumor stages, with the poorest outcomes observed in stages II and III." (PMID 40724850, 2025). "The association between PIEZO1 and tumor microenvironment scores (Stromal, Immune, ESTIMATE) or immune checkpoint markers (CD274, CTLA4, LAG3, PDCD1, PDCD1LG2) were analyzed using the R language." (PMID 40977743, 2025). "Previous studies have established that mechanical stress activates Akt signalling through Piezo1, a pathway implicated in cardiovascular protection, tumour progression and fibrotic disease." (PMID 41332397, 2025). "Secondly, we used ROC curves to assess the diagnostic value of PIEZO1, and found that PIEZO1 showed good diagnostic value in 16 tumor types with AUC > 0.700." (PMID 40977743, 2025). "Aberrant NFAT activation is linked to tumor progression and fibrosis, indicating Piezo1’s potential role in pathological gene reprogramming." (PMID 41195420, 2025). "In these tumor types, elevated PIEZO1 expression has been consistently associated with enhanced tumor aggressiveness and poorer clinical outcomes, highlighting the context-dependent role of PIEZO1 across different malignancies." (PMID 40724850, 2025). "These associations align with poor clinical outcomes, positioning PIEZO1 as a promising biomarker for tumor aggressiveness and prognosis." (PMID 40977743, 2025). "Research has found that Piezo1 regulates the polarization of tumor-associated macrophages, promoting the formation of the M2 immune-suppressive phenotype, thereby inhibiting anti-tumor immune responses." (PMID 41195420, 2025). "In contrast, ultrasound‐treated tumor cells showed a strong association of Piezo1 with the enlarged adhesions at the cell periphery." (PMID 40060768, 2025). "For instance, PIEZO1, a closely related homolog, can mediate similar Ca2+ influx and has been implicated in tumor growth, angiogenesis, and migration." (PMID 41327436, 2025). "PIEZO1 expression status was significantly associated with clinicopathological characteristics, including tumor grade (p = 0.0147)." (PMID 40724850, 2025). "Piezo1 in Tumor Cells: Dysregulated function of Piezo1 in tumor cells has been closely associated with tumor initiation, progression, and metastasis." (PMID 40821847, 2025). "The expression of Piezo1 is highly correlated with tumor microenvironment-related genes that encode proteins involved in ECM organization, angiogenesis, and cell migration." (PMID 39539343, 2024). "The expression of Piezo1 in tumors and its association with tumor stage, grading and patient survival." (PMID 38690080, 2024). "Second, overexpression of the Piezo1 channel was associated with the proliferation and growth of tumor cells." (PMID 38690080, 2024). "In pancreatic ductal adenocarcinoma, the Piezo1-deficient group had slower tumor growth and reduced MDSCs." (PMID 38690080, 2024). "For example, in tumor epithelial cells and immune cells, it is known that the loss of Piezo1 induces a fast integrin-independent migration together with the modulation of integrin expression and cell adhesion." (PMID 38339025, 2024). "A growing body of evidence in recent years has linked the aberrant functional expression of Piezo1 to tumor malignancy in different types of cancer." (PMID 38581527, 2024). "In recent years, an increasing number of studies have linked the Piezo1 channel with tumor development." (PMID 38690080, 2024).
tumor (continued). "When the tumor invades into a well perfused area, Piezo1 reactivates due to the loss of the acidified environment." (PMID 38690080, 2024). "Piezo1 expression is also augmented in various cancers due to stiffness in the tumor microenvironment, causing further cell proliferation and migration." (PMID 38534326, 2024). "Aberrant expressions of both Piezo1 and Piezo2 genes are in many ways linked to tumor development and metastases." (PMID 36837670, 2023). "A recent study shows that ultrasound wave specifically causes apoptosis of tumor cells, by inducing Piezo1-regulated calcium influx and activating a calpain-dependent mitochondrial pathway." (PMID 37864030, 2023). "The KEGG data suggested that “Inflammatory mediator regulation of TRP channels” seem to be associated with the role of PIEZO1 on tumor oncogenesis." (PMID 35747124, 2022). "Although the rate of tumor growth was significantly faster and greater in Piezo1-/- than in WT mice, IL-12 or anti-TGFβ1 antibody treatment significantly inhibited the tumor growth caused by Piezo1-/-." (PMID 35993548, 2022). "Piezo1, a mechanically activated ion channel, can regulate Ca2+-dependent signaling cascades associated with tumor cell migration by promoting local Ca2+ influx." (PMID 36230965, 2022). "The authors also found that Piezo1-deficient DCs mildly suppressed the DC-mediated anti-tumor response in a syngeneic ovalbumin (OVA) mouse model." (PMID 34831037, 2021). "PIEZO1 is the upstream molecule of integrins and can directly sense the mechanical changes caused by tumour tissue pressure, which makes PIEZO1 a potential biomarker as a therapeutic target." (PMID 32999349, 2020). "Among its functions in the tumour microenvironment, PIEZO1 appears to play a particularly strong role in ECM signalling pathways to regulate tumour-associated tissue remodelling." (PMID 32999349, 2020). "As shown in the results, PIEZO1 expression is positively correlated with genes that are responsible for cell proliferation, tumour-associated tissue remodelling, immune response and tumourigenesis." (PMID 32999349, 2020). "Gene ontology analysis showed that expression of PIEZO1 was correlated with tumour microenvironment-related genes that encode proteins involved in extracellular matrix (ECM) organization, angiogenesis and cell migration." (PMID 32999349, 2020). "In conclusion, our pan-cancer analysis suggests that PIEZO1 is a potential biomarker associated with tumor growth and may act as a candidate for cancer therapy." (PMID 40977743, 2025). "Mechanical stimuli, including stretch and compression, activate Piezo1 and its associated signaling pathways, such as the Akt/mTOR pathway in prostate cancer 106, thereby promoting cell cycle progression and enhancing tumor cell invasion as well as matrix degradation." (PMID 40083943, 2025). "Elevated PIEZO1 expression was associated with advanced tumor grade and stage." (PMID 40977743, 2025). "Moreover, higher PIEZO1 mRNA levels were associated with improved overall survival, suggesting a potential tumor-suppressive function in NSCLC." (PMID 40724850, 2025). "Additionally, in tumor cells, Piezo1 expression is often significantly upregulated and associated with tumor malignancy progression." (PMID 41195420, 2025). "Furthermore, in macrophages, Piezo1 regulates tumor-associated macrophages (TAMs) polarization and functional reprogramming by modulating inflammatory responses and mechanotransduction." (PMID 40821847, 2025). "Although the loss of Piezo1 in small cell lung cancer epithelial cells reduces the integrin affinity and cell adhesion, it simultaneously biases tumor cell migration toward the amoeboid mode, which moves in a more globular morphology depending on actin cytoskeleton rearrangement." (PMID 38690080, 2024).
tumor (continued). "The increased entry of calcium ions after ultrasound is associated with the neighborhood around the tumor cells, and the location of Piezo1 near the tumor cells suggests that Piezo1, by activating the channel, facilitates the entry of calcium ions and thus enhances the therapeutic effect." (PMID 38690080, 2024). "First, Piezo1 is linked to the ability of tumor cells to migrate and invade." (PMID 38690080, 2024). "Finally, the Piezo1 channel has also been linked to the transformation of tumor cells and drug resistance." (PMID 38690080, 2024). "In summary, Piezo1 has an ingenious role in the activation of tumor cell proliferation signals and cell cycle operation, and has been implicated in multiple tumor apoptotic pathways, which is why the effect of Piezo1 on tumor proliferation and apoptosis is so complex." (PMID 38690080, 2024). "Piezo1 is associated with this process and attenuates Rb tumor suppressive potential." (PMID 36230880, 2022). "Piezo1 is expressed in many different tissues, and its activation has been associated with a wide variety of responses in the vascular system, lungs, urinary tract, red blood cells, and even tumor metastasis." (PMID 36361659, 2022). "However, as mechanistic studies are currently limited, further studies are needed to elucidate the molecular mechanisms underlying the effect of Piezo1 in promoting tumor cells proliferation potential." (PMID 36230880, 2022). "Gene ontology analysis shows that high levels of Piezo1 are correlated with tumor microenvironment-related genes that encode proteins involved in ECM organization, angiogenesis and cell migration, including MMPs, mitogen-activated protein kinase (MAPK) family members and PI3K family members." (PMID 36158191, 2022). "Hence, it is reasonable to assume that an elevated level of calpains and the mechanically activated expression of Piezo1 in tumor cells make them more susceptible to the US‐mediated mechanical stresses as compared to the normal cells." (PMID 34589605, 2021). "Moreover, activated Piezo1 reduced MMP, suggesting that Piezo1 was associated with tumor cell death." (PMID 32152662, 2020). "In tumour-associated neutrophils (TANs), Piezo1 activation induces Ca2+-dependent neutrophil extracellular trap formation (NETosis), releasing deoxyribonucleic acid networks that capture circulating tumour cells and facilitate their metastasis and colonization." (PMID 41437911, 2026). "Additionally, in hepatocellular carcinoma, Piezo1 may be involved in tumor-associated angiogenesis driven by matrix stiffness by upregulating VEGF, CXCL16, and IGFBP2." (PMID 41226585, 2025). "Additionally, Piezo1 activation is closely linked to intercellular interactions in the lymph nodes, which can have important implications for the metastasis and growth of tumor cells." (PMID 41195420, 2025). "Emerging evidence demonstrates that Piezo1 is widely expressed across various cellular compartments of the tumour microenvironment (TME), and its elevated expression strongly correlates with adverse clinical outcomes." (PMID 41437911, 2026). "In three-dimensional (3D) matrices, the stiffening of the extracellular matrix (ECM) can activate Piezo1, leading to calcium influx that substantially boosts NK cells’ cytotoxicity and tumor infiltration ability." (PMID 41607548, 2026). "Mechanical stimuli activate Piezo1, promoting macrophage polarization towards an immunosuppressive phenotype and inhibiting T cell tumour-killing capacity, thereby contributing to the formation of the immunosuppressive TME." (PMID 41437911, 2026). "This elevated stiffness can further activate signalling pathways related to tumour cell proliferation and invasion by stimulating the mechanosensor Piezo1, promoting cancer cell proliferation, migration, invasion, angiogenesis and immune evasion." (PMID 41437911, 2026). "In breast cancer, tumour cells experience significant compressive stress, which activates the Piezo1 channel." (PMID 41437911, 2026).
tumor (continued). "Piezo1, acting as a mechanosensor within the tumour microenvironment, serves as a key node linking mechanical cues to immune responses by regulating immune cell function at multiple levels." (PMID 41437911, 2026). "Our observations suggest that the PIEZO1-RHO-ROCK axis links tissue-level forces to persistent tumor-promoting epigenetic changes and merits evaluation as a mechanotherapy target in cancer." (PMID 41779857, 2026). "Piezo1’s structure hinders the design of selective modulators, and delivery systems have yet to achieve tumor-localized delivery to avoid systemic toxicity." (PMID 41607548, 2026). "Nonetheless, under conditions of high tumor matrix stiffness, Piezo1 activation upregulates odd-skipped related transcription factor 2 (Osr2) through the Ca2+-Ca2+/calmodulin-dependent protein kinase II-cAMP response element-binding protein axis." (PMID 41362727, 2026). "Activation of Piezo1 in endothelial and immune cells promotes tumour angiogenesis and immune evasion." (PMID 41437911, 2026). "Under conditions of increased matrix stiffness or inflammatory stimulation, Piezo1 activation promotes IL-12 secretion, driving Th1 cell differentiation and enhancing anti-tumour immunity." (PMID 41437911, 2026). "In this review, we aimed to highlight the molecular mechanisms of Piezo1, systematically elucidating how the mechanical stimulation-Piezo1 signalling pathway within the TME contributes to tumour immune escape and malignant progression." (PMID 41437911, 2026). "As the tumour progresses, increasing matrix stiffness activates macrophage Piezo1, promoting polarization of TAMs towards the M2 phenotype and shifting their function from pro-inflammatory to immunosuppressive." (PMID 41437911, 2026). "As a pivotal mechanosensitive ion channel, Piezo-type mechanosensitive ion channel component 1 (Piezo1) converts mechanical stimuli into biochemical signals that regulate key oncogenic processes, including tumour cell proliferation, migration and invasion." (PMID 41437911, 2026). "The Piezo1-Ca2+ axis facilitates tumour invasion either by increasing matrix metalloproteinase (MMP) secretion to degrade the basement membrane or by inducing CAFs to produce aligned collagen fibres." (PMID 41437911, 2026). "In the TME, endothelial cells not only promote tumour angiogenesis and form abnormal vascular structures through Piezo1 activation but also facilitate immune evasion through multiple mechanisms." (PMID 41437911, 2026). "As a core member of the mechanosensitive ion channel family, Piezo1-mediated mechanotransduction exerts multidimensional regulatory roles in malignant tumour progression." (PMID 41437911, 2026). "Inhibition of Piezo1 activity enhances T-cell traction forces and augments their tumor-killing capacity." (PMID 41362727, 2026). "The resulting increase in ECM stiffness further activates Piezo1 in tumour cells, creating a vicious cycle." (PMID 41437911, 2026). "Piezo1 significantly promotes abnormal tumour angiogenesis and immune evasion by regulating signal transduction in TAECs." (PMID 41437911, 2026). "As previously discussed, targeting Piezo1 in DCs modulates Th1 and Treg subset differentiation and function, promoting adaptive immune microenvironment remodelling and enhancing anti-tumour immunity." (PMID 41437911, 2026). "During the regulation of inflammatory factor secretion, the high stiffness of tumour tissue activates the Piezo1-Ca2+ axis in CAFs." (PMID 41437911, 2026). "In an orthotopic bladder cancer model, an R11 peptide-modified nanoparticle was developed: the R11 peptide forms hydrogen bonds with integrin β1, enhancing nanoparticle binding to tumour cells via the Piezo1/integrin β1 signalling axis." (PMID 41437911, 2026). "Together, these parallels underscore the potential of PIEZO1 as a key regulator of the tumor microenvironment in ccRCC and highlight its value as a compelling candidate for further functional validation." (PMID 40724850, 2025).
tumor (continued). "The activation and function of Piezo1 show significant heterogeneity across different cell types, particularly evident in its distinct mechanisms of action in tumor cells, immune cells, and stromal cells." (PMID 40821847, 2025). "In NK cells, activation of Piezo1 enhances their cytotoxicity against tumor cells, promotes NK cell infiltration, and improves the efficacy of immunotherapy." (PMID 40821847, 2025). "Although previous studies on PIEZO1 have largely focused on tumor apoptosis and metastasis, its role in regulating cancer stemness has been less examined." (PMID 41533929, 2025). "In terms of therapeutic strategies, Piezo1 inhibitors (such as siRNA interference or small molecule antagonists) have shown potential in vitro and in animal models to suppress tumor growth and enhance chemotherapy sensitivity." (PMID 41195420, 2025). "In clinical samples, regions of YAP nuclear/cytoplasmic overexpression co-localize with high levels of Piezo1 and the proliferation marker Ki-67, while non-tumor tissues lack this signaling axis." (PMID 40821847, 2025). "Against this backdrop, increasing attention has been directed toward Piezo1, a mechanosensitive ion channel, for its emerging roles in both tumor biology and immune regulation." (PMID 40821847, 2025). "Piezo1, a key mechanosensitive ion channel, facilitates the production of tumor-suppressive CM, with its knockdown significantly impairing anti-cancer effects." (PMID 39940798, 2025). "Animal experiments showed that PIEZO1 depletion accelerated the diminishment of bioluminescence signals of tumor cells in the lungs." (PMID 41390768, 2025). "Immunofluorescence analysis of clinical UM specimens revealed that PIEZO1 expression was significantly higher in tumor tissues than in adjacent normal uveal tissues." (PMID 41533929, 2025). "Immunohistochemical analysis revealed cytoplasmic localization of PIEZO1 in both ccRCC tissues and adjacent non-tumor kidney samples." (PMID 40724850, 2025). "Collectively, these findings highlight the multifaceted role of Piezo1, not only as a driver of tumor progression but also as a key modulator of immune cell function, thereby contributing to tumor immune evasion." (PMID 40821847, 2025). "For instance, Piezo1-mediated mechanotransduction helps tumor cells sustain survival advantages under hostile microenvironmental conditions, thereby accelerating tumor progression." (PMID 40821847, 2025). "In tumor cells, Piezo1 movement to the plasma membrane was observed following ultrasound treatment from a diffuse distribution in the cytoplasm." (PMID 40060768, 2025). "The expression patterns of Piezo1 channels are closely related to their roles in regulating cell migration in situ, cell morphology, and tumor growth." (PMID 41017814, 2025). "Piezo1 is a central nexus connecting mechanosensation to cell-fate decisions throughout tumor initiation, progression, and immunoregulation." (PMID 40821847, 2025). "Surprisingly, tumor cells undergo apoptosis through a calpain‐dependent mitochondrial pathway that relies upon calcium entry through the mechanosensitive Piezo1 channels." (PMID 40060768, 2025). "Our analyses aimed to characterize the transcriptional landscape of PIEZO1 and explore its potential regulatory networks in tumor biology." (PMID 40724850, 2025). "Given its dual regulatory roles in tumor biology and immune modulation, targeting Piezo1—such as through combination with programmed death-1 (PD-1) blockade—offers a potential strategy to reverse immunosuppression and enhance antitumor immunity." (PMID 40821847, 2025). "Colony formation and wound healing assays assessed PIEZO1’s in vitro effects on cancer cells, while xenograft models evaluated its in vivo impact on tumor growth." (PMID 40977743, 2025). "Their study revealed that PIEZO1 promotes malignant tumor progression via a mechanotransduction-mediated histone modification signaling axis." (PMID 41533929, 2025).